ENSG00000254979 (novel protein)
Gene: Protein-coding gene on chromosome 11 (57,387,365 to 57,424,059, reverse strand). Ensembl gene ENSG00000254979.
Genetic constraint (gnomAD): Loss-of-function variants: 12 observed, 13.52 expected, observed/expected ratio (o/e) 0.89, 90% interval 0.57 to 1.43. Missense variants: 224 observed, 267.58 expected, observed/expected ratio (o/e) 0.84, 90% interval 0.75 to 0.94. Synonymous variants: 111 observed, 111.45 expected, observed/expected ratio (o/e) 1, 90% interval 0.85 to 1.17.